CST6 (cystatin E/M)
Description:
High affinity inhibitor for cathepsin L, cathepsin L2 (cathepsin V), and legumain. Involved in the regulation of epidermal cornification, and hair follicle morphogenesis and maintenance.
Synonyms: ECTD15
Tractability: Antibody: UniProt places it where antibodies can reach, with medium confidence; UniProt predicts a signal peptide or a membrane-spanning region; its Gene Ontology location is reachable by antibodies, with medium confidence; the Human Protein Atlas places it where antibodies can reach.
Gene: Protein-coding gene on chromosome 11 (66,012,008 to 66,013,505, forward strand). Ensembl gene ENSG00000175315.
Subcellular location: Secreted
Subcellular location (Human Protein Atlas): Plasma membrane; Cytosol; Predicted to be secreted
Gene Ontology:
Molecular function: protein binding; cysteine-type endopeptidase inhibitor activity
Biological process: anatomical structure morphogenesis
Cellular component: extracellular exosome; cornified envelope; extracellular region
Genetic constraint (gnomAD): Loss-of-function variants: 9 observed, 10.48 expected, observed/expected ratio (o/e) 0.86, 90% interval 0.52 to 1.49. The upper end of that interval is the gene's LOEUF score, 1.49, which puts it in group 6 of 6, group 1 being the genes least tolerant of losing a copy. Missense variants: 206 observed, 185.99 expected, observed/expected ratio (o/e) 1.11, 90% interval 0.99 to 1.24. Synonymous variants: 100 observed, 79.35 expected, observed/expected ratio (o/e) 1.26, 90% interval 1.07 to 1.49.
Homologues: Orthologues: chimpanzee CST6 (99% identical), macaque CST6 (95% identical), pig CST6 (78% identical), dog CST6 (74% identical), rat Cst6 (70% identical), mouse Cst6 (69% identical), guinea pig CST6 (64% identical), Caenorhabditis elegans cpi-1 (22% identical), Caenorhabditis elegans cpi-2 (19% identical), Caenorhabditis elegans K08B4.7 (8% identical). Paralogues in human: CST3 (34% identical), CST1 (32% identical), CST4 (30% identical), CST2 (29% identical), CST7 (28% identical), CST11 (27% identical), CST5 (26% identical), CSTL1 (24% identical), CST8 (23% identical), CST9L (19% identical), CST9 (15% identical).
Diseases named in the same sentence as CST6 in open-access papers:
CST6 is named in the same sentence as 82 diseases in open-access papers, as found by Europe PMC text mining. Sharing a sentence is not in itself a finding about the gene and the disease. The quoted sentences say what the papers report.
breast carcinoma (40 papers, 2008 to 2026). "Previously, it was shown that in breast cancer, loss of CST6 led to a subsequent loss of estrogen receptor alpha (ERα)." (PMID 40075680, 2025). "Work by others showed methylation of CST6 to be associated with worse patient prognosis in breast cancer, whereas the encoded protein (cystatin M) inhibited breast cancer cell proliferation, motility and metastasis." (PMID 29720474, 2018). "One of the mechanisms of CST6 downregulation is promoter methylation which was shown to be strongly associated with poor prognosis in operable breast cancers." (PMID 24742492, 2014). "CST6 loss in breast cancers has been shown to be associated with loss of both ERα and the progesterone receptor." (PMID 24742492, 2014). "According to our findings, the diagnostic sensitivity and specificity of CST6 methylation as a biomarker for prediction of relapses and deaths in operable breast cancer seems to be quite promising." (PMID 23088560, 2012). "In breast cancer, several recent studies have indicated that loss of the cysteine protease inhibitor cystatin E/M leads to increased growth and metastasis." (PMID 20074384, 2010). "Previously, it was found that loss of CST6 in breast cancer led to a loss of ERα expression." (PMID 40075680, 2025). "Previously, loss of Cst6 was shown to negatively impact ERα gene expression in breast cancer." (PMID 40075680, 2025). "CST6 is known to contribute to the homeostatis of the skin, but also been implicated in cancer biology, as it is often found to be downregulated, and sometimes completely silenced, in various cancer types such as breast cancer, melanoma, and lung cancer." (PMID 39416432, 2024). "A cluster of tumors, identified as basal-like breast cancers, expresses a hypermethylator signature with a low expression level of six specific genes including CST6 and is associated with an aberrant overexpression of DNA (cytosine-5)-methyltransferase 3β (DNMT3b)." (PMID 33919854, 2021). "Finally, we show that TBX2 and CST6 displayed reciprocal expression in a cohort of primary breast cancers with increased TBX2 expression associating with increased metastases." (PMID 24742492, 2014). "Loss of CST6 expression in breast cancers has been attributed to promoter hypermethylation." (PMID 24742492, 2014). "Recently, TBX2 was also shown to repress NDRG1 and CST6 in breast cancer by recruiting a CoREST repression complex (LSD1, ZNF217 and HDAC1) to their promoters." (PMID 39912718, 2025). "For example, TBX2 interacts with and requires early growth response 1 (EGR1) to inhibit the tumour suppressor genes N-myc downstream-regulated gene 1 (NDRG1) and cysteine protease inhibitor cystatin 6 (CST6) to promote breast cancer cell proliferation." (PMID 39912718, 2025). "Promoter methylation of cell free DNA of the CST6 gene was found to be a potential plasma biomarker for Breast Cancer." (PMID 39484215, 2024). "CST6 protein and peptides limit bone metastases in breast cancer by reducing CTSB activity and osteoclastogenesis." (PMID 37377916, 2023). "The secretory CST6 protein can be internalized into lysosomes of melanoma, breast cancer, and lung cancer cells." (PMID 35881476, 2022). "CST6 was initially identified as a tumor suppressor and an epigenetically downregulated gene in breast cancer." (PMID 33919854, 2021). "Previously we showed that CST6 suppresses bone metastasis of breast cancer and observed a reduction of osteoclasts in the metastases caused by CST6-expressing cancer cells." (PMID 34815788, 2021). "More importantly, the CST6 recombinant protein and peptides showed promising effects to treat in vivo bone metastasis of breast cancer." (PMID 34815788, 2021). "Particularly, we revealed that CST6 showed a higher expression in breast cancer, pancreatic cancer, and prostate cancer, while the expression level of CST6 significantly decreased in liver cancer, lung cancer, melanoma, ovarian cancer, and renal cancer." (PMID 34603393, 2021).
breast carcinoma (continued). "The CST6 promoter methylation status of circulating tumor cells (CTCs) isolated from peripheral blood of breast cancer patients was also analyzed." (PMID 33919854, 2021). "Previously by secretomic profiling, we found that CST6 is downregulated in bone-tropic breast cancer cells and tumor samples." (PMID 34815788, 2021). "An aberrant methylation profile of CST6 was also found in axillary lymph node metastasis in comparison to primary tumor tissue and adjacent normal tissue from the same breast cancer patients." (PMID 33919854, 2021). "Previously we identified CST6 as a secretory protein significantly downregulated in bone-metastatic breast cancer cells." (PMID 34815788, 2021). "Chimonidou and colleagues demonstrated in three studies that methylation status of three tumor-associated genes (CST6, BRMS1, and SOX17) can be detected in circulating tumor cells of breast cancer patients." (PMID 29190932, 2017). "We and others have already shown that detection of CST6 promoter methylation in primary tissues provides important prognostic information in patients with operable breast cancer." (PMID 29069768, 2017). "CST6 promoter methylation was observed in 11/31 (35.5%) patients with early breast cancer and 16/32 (50.0%) patients with metastasis." (PMID 29069768, 2017). "In a screen for proteins related to breast cancer metastasis to bone tissue, an inhibitor of several cathepsin proteases, cystatin-M (CST6), was observed to be downregulated." (PMID 24713112, 2014). "We show for the first time that TBX2 mediated transcriptional repression of CST6 is an important event for maintaining the tumorigenesis of a subset of breast cancers, through aberrant activation of the protease LGMN." (PMID 24742492, 2014). "CST6 has been postulated to be a tumor suppressor gene in breast tissue, reducing breast cancer cell proliferation, migration, matrigel invasion, and adhesion to endothelial cells." (PMID 24742492, 2014). "Cystatin 6 (CST6), also called cystatin E/M, was first identified as a cysteine protease inhibitor which showed a significant downregulation in breast cancer mRNA samples compared to matched normal control mRNAs." (PMID 24742492, 2014). "We therefore conclude that CST6 induces an autophagy related series of events culminating in the apoptosis of breast cancer cells." (PMID 24742492, 2014). "We have previously demonstrated that CST6 is hypermethylated in breast cancer tissues and that CST6 promoter methylation provides important prognostic information in patients with operable breast cancer." (PMID 23088560, 2012). "Our group has shown for the first time the prognostic significance of CST6 promoter methylation in patients with operable breast cancer." (PMID 23088560, 2012). "We further applied the developed MS-HRMA assay to evaluate the CST6 methylation status in an independent cohort consisting of 80 FFPE breast carcinomas samples." (PMID 23088560, 2012). "CST6 promoter is highly methylated in cancer, and its detection can provide important prognostic information in breast cancer patients." (PMID 23088560, 2012). "CST6 methylation is an early event in breast cancer, since methylation of the CST6 promoter has already been reported in 7 out of 28 corresponding normal tumor-adjacent breast tissues samples." (PMID 23088560, 2012). "Several groups have reported DNA methylation-dependent silencing of CST6 gene in breast cancer cell lines and primary invasive ductal carcinomas, but the upstream initiators that direct this process have not been elucidated." (PMID 21092257, 2010). "Despite these reports, the majority of studies in other tumor types have found that cystatin E/M exerts a suppressive effect on carcinogenesis and demonstrated growth and metastasis suppressing properties in both breast cancer and glioma." (PMID 20074384, 2010).
breast carcinoma (continued). "Restoration of cystatin E/M expression in breast cancer reduces growth, migration, and Matrigel invasion in vitro, as well as tumor growth and metastatic burden in vivo." (PMID 20074384, 2010). "Cystatin M (CST6) is a recognized breast cancer tumor suppressor gene that was recently reported to be silenced due to promoter hypermethylation in numerous breast cancer cell lines, as well as primary breast tumors." (PMID 18221536, 2008). "CST6, an extracellular polypeptide inhibitor of cysteine proteases, also affects bone metastasis by regulating osteoclastogenesis in many cancers, such as breast cancer and multiple myeloma." (PMID 37476411, 2023). "Further, CST6 is an inhibitor of osteolytic metastasis in breast cancer." (PMID 34194498, 2021). "The aberrant methylation and downregulated expression of CST6 were also found in breast cancer patients, and the expression could reactivate after DNA demethylating agent treatment." (PMID 34603393, 2021). "Next, we tested whether the recombinant CST6 protein could be used to treat bone metastasis of breast cancer." (PMID 34815788, 2021). "Data support that CST6 promoter methylation in cell-free DNA could be a putative novel plasma tumor marker for breast cancer." (PMID 33919854, 2021). "This overexpression rescued mice from osteolytic metastasis and death, while CST6 knock-down markedly enhanced cancer cell bone metastasis and shortened animal survival, sustaining that cystatin M/E is a bona fide suppressor of breast cancer osteolytic metastasis." (PMID 33919854, 2021). "Notably, CST6 has been identified by two independent groups as being differentially methylated between breast cancer and control plasma samples." (PMID 25988180, 2015). "Indeed CST6 was amongst the 10 most hypermethylated genes in comparisons between breast cancers and matched normal breast tissues." (PMID 24742492, 2014). "Moreover, we have recently shown that CST6 promoter was methylated in Circulating Tumor Cells (CTC) isolated from peripheral blood of breast cancer patients, in both groups of early disease and verified metastasis." (PMID 23088560, 2012). "Epigenetic silencing of CST6 gene in breast cancer has been reported by several groups." (PMID 21092257, 2010). "Gene expression data from the microarray analysis of 92 primary breast tumors (from the UNC Microarray Database) were analyzed for expression of the six genes (CEACAM6, CDH1, CST6, ESR1, LCN2, and SCNN1A) whose loss characterizes the hypermethylator phenotype among breast cancer cell lines." (PMID 18221536, 2008). "Later, another study validated CST6 hypermethylation and identified two other TSGs, inter-α-trypsin heavy chain 5 (ITIH5) and Ras association domain family 1 isoform A (RASSF1A), hypermethylated in CTCs isolated from breast cancer patients when compared to the primary tumors." (PMID 37369946, 2023). "A panel of 13 genes, including CST6, may enable breast cancer prediction and patient stratification, based on well-defined DNA methylation profiles, and might be a valuable biomarker for early detection of breast cancer." (PMID 33919854, 2021). "Among these proteins, MET is known to be involved in breast cancer, while little is known about the roles of CPM and CST6." (PMID 41514346, 2026). "We compared the methylation status of three genes, SOX17, CST6 and BRMS1 in primary tumours, corresponding CTCs and ctDNA in 153 breast cancer patients and healthy individuals, by using real time methylation specific PCR." (PMID 29069768, 2017). "Overall, CST6, HOXB4, ITIH5 and RASSF1 were more frequently methylated in CTCs from breast cancer patients compared to MNCs from healthy controls." (PMID 29190932, 2017). "For breast cancer, methylation has been noted in genes including BRCA1, p16, E-cadherin, H-cadherin, ATM, CST6, cyclin D2, PTEN, RASSF1A, APC, RARb2, GSTP1, ER, PR, as well as numerous other genes related to multiple pathways relevant for carcinogenesis." (PMID 24368439, 2014).
breast carcinoma (continued). "In the serum samples, promoter hypermethylation of some studied genes was correlated with clinical parameters (APC with histological grade G2; TIMP3 with late stage of breast cancer; BMP6, CST6, and TIMP3 with lymph node involvement)." (PMID 21283676, 2011). "Using hierarchical clustering in the plasma samples cohort, we found significant promoter hypermethylation of eight genes (APC, BIN1, BRCA1, CST6, GSTP1, P16, P21 and TIMP3) in patients' plasma of breast cancer patients compared with plasma of normal subjects." (PMID 21283676, 2011). "CDH1, CST6, MUC1 and SCNN1A genes, all reported to be aberrantly hypermethylated in breast cancer, were down-regulated in both MDA-MB-231 and Hs578T GLO1-depleted breast cancer cells when compared with control." (PMID 36998085, 2023). "In a pilot study, it was observed that CST6 promoter is hypermethylated in cell-free DNA circulating in the plasma of breast cancer patients, but not in healthy individuals." (PMID 33919854, 2021). "Exogenous expression of wild-type CST6 in TBX2 expressing breast cancer cells resulted in significant apoptosis whilst non-tumorigenic breast cells remain unaffected." (PMID 24742492, 2014). "We show that exogenous expression of wild-type CST6 induces apoptotic effects in TBX2 expressing breast cancer cells but not in non-tumorigenic breast cells." (PMID 24742492, 2014). "Exogenous expression of CST6 in TBX2-expressing breast cancer cells resulted in significant apoptosis whilst non-tumorigenic breast cells remained unaffected." (PMID 24742492, 2014). "Although it has been reported that cystatin E/M is capable of suppressing invasion of breast cancer, its ability to inhibit melanoma progression has not been investigated." (PMID 20074384, 2010). "To achieve a gene panel for developing a breast cancer blood-based test we quantitatively assessed the DNA methylation proportion of 248 CpG sites per sample (total of 31,248 sites in all analyzed samples) on 10 candidate genes (APC, BIN1, BMP6, BRCA1, CST6, ESR-b, GSTP1, P16, P21 and TIMP3)." (PMID 21283676, 2011).